CCL7 (C-C motif chemokine ligand 7)
Diseases named in the same sentence as CCL7 in open-access papers (continued):
Sharing a sentence is not in itself a finding about the gene and the disease.
asthma (15 papers, 2008 to 2024). "Identification of one of the genetic markers of asthma such CCL7 gene in pigtailed monkeys is needed as a first step to use pigtailed monkeys as an animal model of asthma." (PMID 39464671, 2024). "One of the proteins that has been identified that plays role in human asthma reaction is C-C ligand 7 (CCL7)." (PMID 39464671, 2024). "Like the cynomolgus monkey, this similarity suggests pigtailed monkey has the potency of a translational model to study asthma, especially in the context of molecular studies and the role of CCL7 in asthma pathogenesis." (PMID 39464671, 2024). "The CCL7 gene has potential as a genetic marker because of the secreted chemokine that plays a role in asthma." (PMID 39464671, 2024). "In this study, we analyse the CCL7 sequences in a pigtailed monkey like we do in the cynomolgus monkey as an animal model for asthma." (PMID 39464671, 2024). "The aim of this study was to determine the characterisation of the CCL7 gene as a genetic marker of asthma in pigtailed monkeys." (PMID 39464671, 2024). "Since safranal showed effect on reducing mast cell infiltration in OVA-induced asthma model and RNA sequencing reveals regulation of Cxcl10 and Ccl7, we proceed with the in vitro experiment." (PMID 34093515, 2021). "The experimental analysis of PLAG effect on CCL7 expression and eosinophil transmigration in asthma model would be informative for identifying the functional mechanism of PLAG completely." (PMID 27010397, 2016). "Therefore, the pigtailed monkey CCL7 gene has high similarity with H. sapiens, which means that based on molecular similarity, the pigtailed monkey has the potential to be an animal model for asthma study, especially the study of molecular and the role of CCL7 in asthma pathogenesis." (PMID 39464671, 2024). "In a study of childhood asthma, CCL5 and CCL7 were significantly increased in the bronchial alveolar lavage (BAL) fluid of children with asthma and was associated with higher BAL eosinophils." (PMID 36177009, 2022). "To ascertain the mechanisms underlying GLCCI1-mediated regulation of the effects of GCs on chemokines, we began by assessing asthma-related pro-inflammatory chemokines (CCL2, CCL3, CCL4, and CCL7) in lung tissues by RT-PCR." (PMID 34504850, 2021). "Less is known about CCL7 in COPD, but it has been described in other inflammatory diseases including asthma, multiple sclerosis, and rheumatoid arthritis." (PMID 26424214, 2015). "Rapamycin treatment of established asthma, however, increased mRNA levels of CCL11 and did not affect the expression of CCL7 or CCL24." (PMID 22685525, 2012).
glioma (15 papers, 2013 to 2023). A benign or malignant brain and spinal cord tumor that arises from glial cells (astrocytes, oligodendrocytes, ependymal cells). "Survival of C57BL/6 mice orthotopically implanted with KR158B, KR158B CCL2 KD, and KR158B CCL7 KD glioma cells were also assessed." (PMID 36685592, 2022). "KR158B and KR158B CCL7 KD glioma cells were orthotopically implanted in Ccr2WT/RFP/Cx3cr1WT/GFP mice." (PMID 36685592, 2022). "KR158B-CCL2 and -CCL7 knockdown murine gliomas contain equivalent percentages of CCR2+/CX3CR1+ MDSCs compared to KR158B gliomas." (PMID 36685592, 2022). "To test the concept that CCL2 and CCL7 drive the recruitment of CCR2+/CX3CR1+ cells into the glioma microenvironment, we took a combinatorial targeting approach in vivo." (PMID 36685592, 2022). "KR158B, KR158B CCL2 KD or KR158B CCL7 KD glioma cell lines were implanted in Ccr2+/RFP/Cx3cr1+/GFP mice, and flow cytometry analysis of tumors and bone marrow was conducted 4.5 weeks post-implantation." (PMID 36685592, 2022). "Inexplicably, genetic knockdown of IL-33 results in elevated CCL7 in glioma cells and further promotes microglial migration." (PMID 36439205, 2022). "The lack of effect observed following the implantation of individual CCL2 or CCL7 knockdown gliomas suggested a potential chemokine ligand redundant mechanism utilized by the KR158B cells to recruit CCR2+/CX3CR1+ cells to the TME." (PMID 36685592, 2022). "Conversely, there was a significant reduction (p=0.003) from mean 25.8% to mean 10.8% glioma infiltrating CCR2+/CX3CR1+ cells when comparing KR158B + IgG vs. CCL7 KD + αCCL2 antibody arms." (PMID 36685592, 2022). "Furthermore, glioma cells rich in IL-33 have high CCL7 expression levels and thus promote microglial infiltration." (PMID 36439205, 2022). "Moreover, OAT-1746 treatment affects the expression of genes involved in leukocyte chemotaxis (Ccl2, Ccl7, Ccl17) and supporting glioma migration and invasion (Cme1, S100a4 and Mmp14)." (PMID 34504786, 2021). "Chemoattractants such as MCP-1 (CCL2), MCP-3 (CCL7), SDF-1 (CXCL12), CX3CL1, POSTN, GM-CSF, M-CSF (CSF-1) and EGF produced by glioma cells actively recruit TAMs and thus promote tumor growth." (PMID 37705736, 2023). "(1c), the first term represents glioma recruitment of MDSCs to the microenvironment by secreting the chemokines CCL2 and CCL7, which are ligands for the CCR2 receptor expressed by MDSCs." (PMID 38099947, 2023). "Recombinant and glioma-derived CCL2 and CCL7 induce the migration of CCR2+/CX3CR1+ MDSCs with similar efficacy." (PMID 36685592, 2022). "CCL2 and CCL7 are produced, at least in part, by glioma cells and our study indicates that CCL2 and CCL7 function in a redundant manner to induce the migration of CCR2+/CX3CR1+ M-MDSCs into the glioma microenvironment." (PMID 36685592, 2022). "ELISA analysis of the conditioned media of KR158B cells determined that after 24 hours, glioma cells plated at 500 cells/uL had produced 11.1ng/mL of CCL2 and 1.9ng/mL of CCL7." (PMID 36685592, 2022). "On the other hand, glioma-cells release chemoattractant molecules that recruit TAMs and promote tumor growth: CCL2, CCL7 (or MCP-3), IL-33, GDNF (Glial cell line-derived neurotrophic factor), MCP-1 (CCL2), SDF-1 (CXCL12), CSF-1 (M-CSF), GM-CSF, and EGF." (PMID 35269652, 2022). "CCR2+/CX3CR1+ cells are also reduced within KR158B gliomas upon combination targeting of CCL2 and CCL7." (PMID 36685592, 2022). "Upon validating CCR2+/CX3CR1+ cell migration to the conditioned media of KR158B and KR158B CCL2 KD glioma cell lines, we sought to determine whether the migration was exclusively mediated by CCL2 and/or CCL7." (PMID 36685592, 2022). "It is known that CCL2 and CCL7 are expressed by tumor and non-tumor cells within the glioma microenvironment." (PMID 36685592, 2022).
glioma (continued). "Using a preclinical glioma model, we demonstrate that CCR2+/CX3CR1+ cells are sourced from the bone marrow, suppress both CD4+ and CD8+ T cells, migrate to CCL2 and/or CCL7 in a CCR2-dependent manner, and are reduced in the glioma microenvironment through combination targeting of CCL2 and CCL7." (PMID 36685592, 2022). "To evaluate whether KR158B tumor cells are active contributors in the recruitment of CCR2+/CX3CR1+ cells, we tested whether glioma cells produced and secreted CCL2 and CCL7." (PMID 36685592, 2022).
viral infection (15 papers, 2017 to 2026). "The chemokine CCL7 (MCP3) is known to promote the recruitment of many innate immune cell types including monocytes and neutrophils to sites of bacterial and viral infection and eosinophils and basophils to sites of allergic inflammation." (PMID 30671055, 2018). "The chemokines CCL7 and CCL12 are known to promote the recruitment of many innate immune cell types including monocytes and neutrophils to sites of bacterial and viral infection and eosinophils and basophils to sites of allergic inflammation." (PMID 35033010, 2022). "During the early stage of viral infection, cytokines (IL-1, IL-2, IL-8, IL-10, CCL2, CCL7, IFN-α, IFN-β, and TNF-α) have essential functions in the recruitment of immune cells, defense against the infection, and promotion of inflammation." (PMID 34603560, 2021). "The formation of super-enhancers governing CXCL9/10/11, CCL7/8/13, IFITM1/2/3, OAS1 genes, but not housekeeping genes, was robustly decreased in SAFA mutation cells after virus infection." (PMID 35658050, 2022). "The viral infection also led to common alterations in some genes and signaling pathways in both iM1φ and iM0φ cells, such as IL1A, IL1B, CCL7, chemokine-mediated signaling, viral protein interaction with cytokine–cytokine receptor, and Toll-like receptor signaling." (PMID 35440562, 2022). "Upregulated expression of cytokines, chemokines and growth factors was commonly observed in patients and animals with lymphopenia induced by viral infection, including IL-2, IL-6, IL-12, IL-18, IL-1β, IFN-γ, CCL2/MCP-1, CXCL1, CXCL8/IL-8, CCL3/MIP-1-α, CCL7/MCP-3, CXCL10/IP-10 and CXCL9/MIG." (PMID 34578457, 2021).
myocardial infarction (12 papers, 2013 to 2025). Gross necrosis of the myocardium, as a result of interruption of the blood supply to the area, as in coronary thrombosis. "Elevated circulating CCL7 levels are observed in patients with acute myocardial infarction and can be used as a predictor of the risk of death or recurrent myocardial infarction." (PMID 36109744, 2022). "Increased CCL7 levels are detected in local extracellular vesicle generation in the infarcted heart coordinates of cardiac inflammation after myocardial infarction." (PMID 36109744, 2022). "Increased serum levels of CCL7 also constitute a predictor of increased cardiovascular morbidity and mortality in patients with acute myocardial infarction." (PMID 34830700, 2021). "Remarkably, high circulating concentrations of CCL7 and the B cell longevity factor BAFF in patients with acute myocardial infarction predict increased risk of death or recurrent myocardial infarction." (PMID 29868023, 2018). "Most CCL7-related studies on cardiovascular disease have been performed in myocardial infarction." (PMID 36109744, 2022). "The authors further found that the circulating concentrations of CCL7 and BAFF in patients with acute myocardial infarction were markedly higher compared to healthy controls, and elevated levels of CCL7 and BAFF always predicted an increased risk of death or recurrence of myocardial infarction." (PMID 35350762, 2022). "Notably, the production of CCL7 by B cells has been described in sterile inflammation in other contexts, for example, ischemia-reperfusion injury in myocardial infarction." (PMID 32737150, 2020). "Taken together, these findings suggested that IFN-β-responsive MICFs recruit monocytes/macrophages after myocardial infarction, and macrophages secreted IFN-β phosphorylate STAT1 in MICFs which further increases the expression of Ccl2, Ccl7, and Ccl12, forming a positive feedback loop." (PMID 38530808, 2024). "Following a myocardial infarction, classical monocytes are recruited within the first few hours, and their egression from the bone marrow is in principle controlled by the chemokine receptor CCR2 and its ligands CCL2 (or MCP-1) and CCL7 (or MCP-3)." (PMID 27478854, 2016). "In a study about myocardial infarction, cardiomyocyte-derived large EVs, but not small EVs, modulate the release of CCL2, CCL7, and IL-6 from cardiac monocytes." (PMID 40995365, 2025).
Stroke (12 papers, 2013 to 2025). Sudden impairment of blood flow to a part of the brain due to occlusion or rupture of an artery to the brain. "In order to identify the MC-derived products that influence stroke pathology, BMCMCs derived from two candidate factor-deficient mice (IL-6 and CCL7) were injected into the meninges of MC-deficient mice." (PMID 31001088, 2019). "The administration of recombinant CCL7 counteracts the neuroprotective effects of lactate, highlighting the critical role of the HIF-1α–CCL7 axis in modulating neuroinflammatory responses following stroke." (PMID 41184254, 2025). "By contrast, MC-derived CCL7 had less of an effect on stroke pathology." (PMID 31001088, 2019). "Genes related to inflammation such as Ccl5, Cxcl5, Il1a, Tnfsf10, Nfkb1, Tnfrsf1b, Ccr7, Tnfrsf9, Ccl7, Il1b, Il6, and Ccl24 were also downregulated upon MMP-3 KO in male stroke brains." (PMID 39000490, 2024). "When comparing SHR and WKY subjected to stroke, we observed a significantly higher expression of CCL2, CCL7, and CXCL2 in SHR." (PMID 26640428, 2015). "However, the expression of CCL2, CCL3, CCL4, CCL7, and CXCL2 was strongly increased after stroke, whereas CCL19, CCL20, and CXCL5 expression levels were not changed." (PMID 26640428, 2015).
diabetes (11 papers, 2014 to 2024). "In type 2 diabetes, CCL7 is associated with adipose tissue inflammation and insulin resistance, indicating its involvement in metabolic syndrome and diabetes development." (PMID 39691364, 2024). "Chemokine CC motif ligand 7 (CCL7) is believed to be associated with cardiovascular disease, diabetes mellitus, and kidney disease." (PMID 36109744, 2022). "Further analysis focusing specifically on chemokines and their receptors also revealed a significant increase in the expression of CCL5 and CCL7 in rat retinas with 4 weeks of diabetes." (PMID 25329075, 2014). "CCL7 can summon macrophages and monocytes, amplify inflammatory processes and contribute to disease progression in kidney diseases, cardiovascular diseases, and diabetes mellitus." (PMID 38235001, 2023). "Cardiac diastolic abnormality and CCL7 were also independently associated in a subset of young type 1 diabetic patients during acute diabetic ketoacidosis, suggesting the potential link of CCL7-related systemic inflammation with the presence of cardiac diastolic dysfunction." (PMID 36109744, 2022).
osteosarcoma (10 papers, 2018 to 2025). A usually aggressive malignant bone-forming mesenchymal neoplasm, predominantly affecting adolescents and young adults. "C-C motif chemokine ligand 7 (CCL7) is a chemotactic factor of the CC subfamily and an attractant of monocytes initially found in the culture supernatant of osteosarcoma cells." (PMID 36118415, 2022). "CCL7 is initially found in human osteosarcoma cells with potent chemotaxis of leukocytes." (PMID 34189838, 2021). "CCL7 (monocyte chemoattractant protein 3, MCP-3) was initially isolated and identified in osteosarcoma cell-conditioned medium." (PMID 41430036, 2025). "Prominently, we observed persistently elevated levels of eotaxin/CCL11, CCL2, CCL7, CXCL1, CXCL10 and BAFF in the DIPG, ALL, and aggressive osteosarcoma models, the same three models that also exhibit cognitive deficits." (PMID 38798554, 2024). "CCL7 (monocyte chemoattractant protein-3, MCP-3), first characterized from osteosarcoma supernatant, is a member of the MCP subfamily and also includes CCL2 and CCL8." (PMID 36830702, 2023). "CCL7, also known as MCP-3, was a chemotactic cytokine first discovered in the supernatants of human osteosarcoma cells (MG-63)." (PMID 35281057, 2022). "Chemokine (C-C motif) ligand 7 (CCL7), also known as monocyte chemotactic protein 3 (MCP-3), is a member of the CC subfamily that was first characterized from osteosarcoma supernatant." (PMID 29915688, 2018). "Similarly, comparing CSF cytokine/chemokine elevations in aggressive osteosarcoma and ALL models following tumor-clearing CAR T cell therapy here, many shared but also some distinct changes are observed, such as elevated CCL7 and BAFF in the ALL model but not the aggressive osteosarcoma model." (PMID 38798554, 2024).
Sepsis (10 papers, 2012 to 2026). Sepsis is defined as life-threatening organ dysfunction caused by a dysregulated host response to infection. "While HSCs remain largely quiescent during homeostasis, after sepsis, they become the liver's central signaling hub and broadcast potent fibrogenic and chemotactic signals (e.g., Ccl7) to surrounding cells." (PMID 42274561, 2026). "It is noteworthy that mice with specific inhibition of endothelial-derived CCL7 exhibit reduced severity of septic ALI, underscoring the critical role of CCL7 in the progression of sepsis." (PMID 40755420, 2025). "In both neonatal mouse sepsis model and septic preterm infants, CCL3, CCL7, and CXCL10 were similarly up-regulated in blood and brain, promoting neutrophil migration across the BBB and exacerbating brain inflammation." (PMID 40254577, 2025). "During the course of LPS sepsis (0–36 hpi), most PICCs reached the first and second peak at 6 and 16 hpi, respectively, with IL-6, IL-18, CCL5, CCL7 and CXCL1 sustaining at plateau at 36 hpi." (PMID 37332010, 2023).
colitis (9 papers, 2017 to 2024). Inflammation of the colon. "The FBXW7/EZH2/CCL2/CCL7 pathway has been shown to exacerbate colitis severity by recruiting CX3CR1 proinflammatory MPhs." (PMID 39568749, 2024). "The secondary BAs consistently showed a significant reduction in the mRNA levels of pro-inflammatory cytokines (Il6, Il1β, Tnfα) and some monocytes-related chemokines (Ccl2, Ccl7, Ccl8) in colitis mice." (PMID 36050867, 2022). "As in murine colitis, CCL7, CCL8, and CXCL1 were all significantly increased in active IBD vs. quiescent IBD and controls." (PMID 30542349, 2018). "After 7 days of induced colitis, upregulation of the expression of 22 genes (Ccl2, Ccl3, Ccl4, Ccl5, Ccl6, Ccl7, Ccl12, Ccl17, Cxcl1, Cxcl2, Cxcl6, Cxcl9, Cxcl11, Ccr1, Ccr2, Ccr3, Ccr5, Ccr8, Cxcr2, Csf3, Osm, and Spp1) was observed in the CβG− group compared to the HβG- control group." (PMID 35163326, 2022). "In addition, a study demonstrated that there were significantly enhanced gene and/or protein expression of chemokines CCL2 and CCL7 in colitis patients." (PMID 28698550, 2017). "PSMP might trigger the earlier-arriving Ly6ChiCCR2+ monocyte migration from the circulation into the tissue and synergize with CCL2 and CCL7 to promote colitis." (PMID 28698550, 2017). "Thus, further investigation is necessary to determine the synergistic role of PSMP, CCL2 and CCL7 in colitis as well as determining whether they represent the therapeutic targets." (PMID 28698550, 2017). "It has been reported that FBXW7 plays a key role in regulating colitis by inducing CCL2 and CCL7 expression in macrophages and promoting the accumulation of pro-inflammatory mononuclear macrophages." (PMID 35419455, 2022). "A range of monocyte and neutrophil attracting chemokines (Ccl7, Ccl8, Cxcl1) were more highly expressed in macrophages compared to monocytes from both steady state and DSS colitis." (PMID 30542349, 2018). "The importance of CCL7, CCL8, CCL12, and CXCL1 to mediate colitis inflammation, and the consequence of enhanced monocyte expression of these chemokines on pathology, is not known." (PMID 30542349, 2018). "Although it has been reported that CD169+ macrophages express Ccl2, Ccl7, and Ccl8 during colitis (the contribution of monocytes was not considered), and analysis of colon IBD sections has suggested CCL8 as the greatest up-regulated chemokine released from inflammatory cells." (PMID 30542349, 2018). "We speculated that the redundancy of PSMP, CCL2 and CCL7 in colitis might result in that CCR2 but not the CCL2 is vital to the progression of colitis." (PMID 28698550, 2017).